NLRX1 (NLR family member X1)
Diseases named in the same sentence as NLRX1 in open-access papers (continued):
Sharing a sentence is not in itself a finding about the gene and the disease.
infection (continued). "Previous proteomics analyses have revealed that the differentially expressed protein NOD–like receptor X1 (NLRX1) located in the mitochondria participates in several important antiviral signaling pathways in PAstV–4 infection, which are closely related to mitophagy." (PMID 38891045, 2024). "We speculated that PAstV–4 infection activated mitochondrial autophagy to resist host innate immunity through the up-regulation of NLRX1, thereby promoting its replication." (PMID 38891045, 2024). "Hence, in this study, we examined the impact of NLRX1 on PAstV–4 replication and further investigated its regulatory role in disrupting intestinal mucosal barrier function induced by PAstV–4 infection." (PMID 38891045, 2024). "Thus, we measured IFNβ, IL-6 and TNFα cytokine production at 24 hours post-infection in both female and male WT and Nlrx1-/- BMDMs infected with LgyLRV1+ parasites or stimulated with poly I:C." (PMID 35651602, 2022). "Although previous reports have not described a link between sex and NLRX1, oppositely to females, infection of Nlrx1-deficient male mice did not result in an exacerbated disease outcome." (PMID 35651602, 2022). "In view of the close relationship of NLRX1, VPS25, and PIP4K2B with mitophagy, we speculate that PAstV/SH/2022/CM1 infection may cause mitochondrial injury—mitophagy—to resist the innate host immunity." (PMID 35891364, 2022). "Thus, we infected WT and Nlrx1-/- female BMDMs with LgyLRV1+ or stimulated them with poly I:C and measured pro-inflammatory cytokines in the cell-free supernatant at 24 hours post-infection." (PMID 35651602, 2022). "Similar to macrophages, epithelial cells and fibroblasts are extensively studied cells in the field of NLRX1 biology and the results further confirm that the role of NLRX1 might differ depending on the cell type and the applied stimuli or infection." (PMID 33525671, 2021). "Interestingly, NLRX1 was found to act as a double-edged sword in gingival epithelial cells upon infection with the oral commensal Fusobacterium nucleatum." (PMID 33525671, 2021). "Furthermore, rhinovirus promotes virus-induced epithelial barrier disruption via NLRX1, whereas SIV upregulates NLRX1 expression in the early phase of the infection to potentiate viral replication." (PMID 33525671, 2021). "The log2FC of TLR2 and NLRX1 between two groups were significant (1.06 and 0.65, respectively), suggesting that gene expression changes in these genes were part of the response in the host to adapt the dosing instead of the pathological infection." (PMID 33809523, 2021). "Interestingly, NLRX1 protected against mitochondrial injury in both infection, and in in vitro models of injury by sodium azide or glucose starvation." (PMID 33344269, 2020). "Similarly, a significant increase in Rab7-positive compartments containing GAS in NLRX1 KO cells was observed, as compared to that in wild-type cells, at 120 min after infection." (PMID 30488027, 2018). "Hence, the present data indicate that FAF1 targets NLRX1 to regulate type I IFN production upon infection with RNA virus only." (PMID 28542569, 2017). "Infection with Shigella, which results in a dramatic collapse of the mitochondrial network, had similar effects in WT and NLRX1-deficient cells (data not shown)." (PMID 24867956, 2014). "Though only a small amount of evidence supports the importance of NLRX1-mediated ROS production during infection, this is most likely due to the recent idea that NLRX1 could be an important mediator of mitochondrial-ROS production during infections." (PMID 21339989, 2011). "This might suggest a potentially significant role for NLRX1 in the context of PAstV–4 infection." (PMID 38891045, 2024). "In addition, due to its localization at the mitochondria, the central hub of metabolism and immunity, several studies suggest a role for NLRX1 in the maintenance of mitochondrial physiology, function, and reactive oxygen species (mtROS) production following infection or injury." (PMID 35651602, 2022).
infection (continued). "Due to substantiated evidence that NLRX1 can be suppressed in an H. pylori dependent manner, we hypothesized that NLRX1 represents a central molecular checkpoint involved in the fate of bacterial burden and macrophage responses during infection." (PMID 26367386, 2015). "Modulation of IFN responses is also predicted to occur through NLRX1 negative regulation of MAVS/RIG-I and NF-κB following SeV infection, vesicular stomatitis virus (VSV), and encephalomyocarditis virus (EMCV) infection." (PMID 40356929, 2025). "In summary, this study first proposed that PAstV−4 infection impaired the mucosal barrier function of Caco−2 cells by activating the ERK/MLCK pathway, and NLRX1 played a vital regulatory role in this network." (PMID 38891045, 2024). "PAstV−4 infection also resulted in the up-regulation of LC3II proteins, and this effect was inhibited by treatment with siRNA/NLRX1." (PMID 38891045, 2024). "Moreover, the ligand or activating signal of NLRX1 upon infection remains unknown." (PMID 36797302, 2023). "Differences in metabolic rates were not linked to mitochondrial numbers or to impairment of mitochondrial structure since Nlrx1-deficient cells had less mitochondria and produced less mtROS than WT cells independently of sex and no structural defects were observed upon LgyLRV1+ infection." (PMID 35651602, 2022). "In LgyLRV1+ infection, the exact mechanism of type I IFN regulation by NLRX1 is yet to be further elucidated." (PMID 35651602, 2022). "Therefore, we investigated whether infection with Lgy regulated Nlrx1 expression." (PMID 35651602, 2022). "In regulating microbe-elicited ROS production during an antimicrobial response, many studies showed that host PRRs (mainly TLR2, TLR4, NOD2, NLRX1, and NLRP3) and redox modulation alleviated pathogen infection." (PMID 34299310, 2021). "At 30 and 60 min after infection, the percentage of EEA1-positive compartments containing GAS in NLRX1 KO cells was significantly increased compared to that in wild-type cells." (PMID 30488027, 2018). "Moreover, the knockdown of NLRX1 hindered the expression of p−ERK and p−MLC induced by PAstV−4 infection." (PMID 38891045, 2024). "We did not observe differences in parasite burden in the establishment of infection (8 hours p.i.) suggesting that NLRX1 did not affect the phagocytic capacity of BMDMs." (PMID 35651602, 2022). "In addition, the NOD-like receptor X1 (NLRX1) in the mitochondria was activated and participated in several important antiviral signaling pathways after the PAstV/CH/2022/CM1 infection, which was closely related to mitophagy." (PMID 35891364, 2022). "In contrast, at 24 hours post infection, the absence of NLRX1 resulted in a decreased number of parasites per cell." (PMID 35651602, 2022). "To further confirm the role of NLRX1 in regulation of inflammation, we collected non-infected and infected footpads at the peak of infection." (PMID 35651602, 2022). "Similar to Ifng, BMDM lacking NLRX1 produced significantly higher amounts of ROS when compared to wild type macrophages during infection with intracellular H. pylori." (PMID 26367386, 2015). "Similarly, we did not observe any significant changes in NLRX1 protein levels at 8 or 24 hours p.i., suggesting a transcriptional regulation of NLRX1 only in the early phase of infection with LgyLRV1+ parasites or after poly I:C treatment." (PMID 35651602, 2022). "The expression level of NLRX1 may be regulated by early, negative feedback circuitry induced by infection." (PMID 34201826, 2021). "However, more recently NLRX1 has been shown to also regulate apoptosis through mechanisms that are independent of RIG-I/MAVS and NF-κB following infection with influenza virus." (PMID 40356929, 2025).
cancer (20 papers, 2014 to 2026). A tumor composed of atypical neoplastic, often pleomorphic cells that invade other tissues. "When NLRX1 is expressed in a healthy cell, it can repress cancer-associated characteristics through inhibition of epithelial-mesenchymal transition (EMT) and metastasis." (PMID 40700427, 2025). "Here, we use a murine pancreatic ductal adenocarcinoma cell line (Pan02) to explore how the overexpression or partial loss of NLRX1 impacts the cancer-associated phenotypes of Pan02 cells." (PMID 37342194, 2023). "Considering the impact NLRX1 demonstrated on several cancer-associated phenotypes in our Pan02 cells, we next collected RNA from Pan02OE, Pan02OE-CTL, Pan02KD, and Pan02KD-CTL cells for transcriptomics analysis (ClariomS)." (PMID 37342194, 2023). "Our results demonstrate that NLRX1 diminishes the cancer-associated phenotypes of Pan02 cells and protects against cancer-associated biological functions through the regulation of NF-κB, MAPK, AKT, inflammasome, and immune recognition/activation signaling." (PMID 37342194, 2023). "Cancer cells are characterized by high glycolytic activity and it was observed that the inhibition of glycolysis is associated with decreased NLRX1 expression." (PMID 33525671, 2021). "The loss of NLRX1 is associated with more severe inflammation and tissue damage in different models of inflammation such as cancer." (PMID 33344269, 2020). "These two publications suggest that NLRX1 functions as a tumor suppressor by decreasing cancer-associated inflammation (IL-6 and TNFα) through effects on NF-κB signaling." (PMID 29535731, 2018). "Together, these results identify NLRX1 as a critical mitochondrial protein implicated in the regulation of apoptosis in cancer cells." (PMID 24867956, 2014). "However, several studies have also characterized this mechanism underlying NLRX1's role as a tumor suppressor in various types of cancer." (PMID 31681307, 2019). "Indeed, the findings of increased inflammation in mice with NLRX1-deficient epithelial cells are in line with two reports of the role of NLRX1 in cancer." (PMID 29535731, 2018). "Our above results suggest that NLRX1 might differentially control apoptotic programs in cancer cells over normal cells, which would affect cancer susceptibility." (PMID 24867956, 2014). "For instance, inducing cancer cell death by extrinsic apoptotic stimuli (such as TNF or TRAIL) might lead to the selection of cancer cells with increased NLRX1 expression that in turn would be highly susceptible to nutrient withdrawal or intrinsic stresses, such as ER stress." (PMID 24867956, 2014). "Typically, NLRX1 displayed the property of a tumor suppressor and the expression level of NLRX1 was blunted in multiple types of cancers [35,]." (PMID 37574163, 2023). "The role of NLRX1 in cancer remains highly enigmatic, with some studies defining its roles as a tumor promoter, while others characterize its contributions to tumor suppression." (PMID 37342194, 2023). "In cancer cells, the removal of extracellular glucose or the addition of the glycolysis inhibitor 2-deoxyglucose (2-DG) significantly reduced NLRX1 expression in both primary- and SV40-transformed MEFs." (PMID 34697412, 2022). "In cancer, NLRX1 has been shown to downregulate key cytokines that are important in cancer progression, such as tumor necrosis factor (TNF) and interleukin (IL)-6." (PMID 34697412, 2022). "The Nlr family member X1 (Nlrx1) is an immuno-metabolic hub involved in mediating effective responses to virus, bacteria, fungi, cancer, and auto-immune diseases." (PMID 34790195, 2021). "An indirect effect seems more likely, given that cancer studies reported decreased Akt activation with increased forced NLRX1 expression." (PMID 33362773, 2020). "Nlrx1 is a known negative regulator of inflammatory aspects of the immune system in response to viruses, bacteria, and cancers." (PMID 32956405, 2020).
cancer (continued). "NLRX1 appears to maintain the crosstalk between mitochondrial metabolism and lysosomal function to modulate key cancer hallmarks." (PMID 31681307, 2019). "Our data analysis revealed that NLRX1 is differentially regulated in a diverse range of human cancers." (PMID 27105514, 2016). "To better characterize the role of NLRX1 in cancer, we subjected Nlrx1−/− mice to a urethane (ethyl carbamate)-induced tumor model." (PMID 27105514, 2016). "The IPA analysis also revealed a significant increase in TNF signaling, which is consistent with the recent study that suggested NLRX1 functions as a tumor suppressor through modulating this pathway in cancer cells." (PMID 27105514, 2016). "To gain broader insight into the contribution of NLRX1 in cancer, we conducted a retrospective evaluation of publically available gene expression metadata compiled from 18 human studies." (PMID 27105514, 2016). "The ability for NLRX1 to inhibit MAVS and the subsequent IFN-I signaling has also been implicated in persistent Hepatitis C (HCV) infections, which can increase the risk for many types of cancer." (PMID 37342194, 2023). "Indeed, early studies in cancer cells demonstrated that NLRX1 promoted glycolysis and displayed glucose-dependent expression." (PMID 37574163, 2023). "Besides CRC, NLRX1 was also shown to inhibit the development of other types of cancers, such as histolytic sarcoma and hepatocellular carcinoma." (PMID 37574163, 2023). "In summary, these results highlighted the importance of NLRX1 as a tumor suppressor gene and introduced innovative cancer therapy strategies that may target NLRX1-regulated oncogenic pathways." (PMID 37574163, 2023). "Indeed, the expression of NLRX1 in various human neoplasms compared to healthy tissue can range from almost 3-fold increased to almost 9-fold decreased based on the type of cancer." (PMID 37342194, 2023). "Similarly, in other cancer cell lines, NLRX1 downregulated the mitochondrial respiratory complex I and III activity to promote the metabolic switch towards aerobic glycolysis." (PMID 33344269, 2020). "NLRX1 mediated modulation of ROS production by the mitochondria has significant implications in multiple biological functions, including anti-viral immunity and cancer." (PMID 31681307, 2019). "Furthermore, intriguing data has recently revealed that NLRX1 also plays a role in mitophagy in the context of both infectious disease and cancer." (PMID 31681307, 2019). "Numerous important signaling molecules are dependent on NAD+ as a co-factor in their mechanisms of action, such as PARP1, which is involved within DNA damage repair and could be an additional linkage between NLRX1 and cancer." (PMID 29535731, 2018). "We anticipate that future studies will better define the role of NLRX1 in cancer." (PMID 27105514, 2016). "Histopathology analysis also revealed an overall reduced pathology and absence of high grade carcinoma lesions in NLRX1-deficient mice, suggesting that NLRX1 deficiency reduces cancer progression in this model." (PMID 24867956, 2014). "Understanding the mechanism through which NLRX1 protects transformed cells from apoptosis may thus open up new strategies for cancer therapy." (PMID 24867956, 2014). "We believe that our data, which show that NLRX1 positively regulates apoptosis induced by intrinsic signals, such as glycolysis inhibition, explain this apparent paradox: because cancer cells heavily rely on glycolysis, they are very sensitive to glycolysis inhibition." (PMID 24867956, 2014). "Interestingly, inhibition of glycolysis lowered NLRX1 expression in cancer cells." (PMID 33525671, 2021). "Moreover, loss of NLRX1 in intestinal epithelial cells altered SIRT1-dependent metabolism and promoted cell proliferation implying potential harmful post-inflammatory effects such as cancer development." (PMID 33525671, 2021).
cancer (continued). "It is possible that the function of NLRX1 is highly dependent on the cellular environment and an altered metabolic state could explain some of the differences observed in the different infectious and cancer models." (PMID 33344269, 2020). "The first observations that NLRX1 could directly regulate metabolism were made in cancer cells." (PMID 33344269, 2020). "Significance: Targeting NLRX1 function could be an interesting strategy against cancer." (PMID 24867956, 2014). "Immunohistochemical analysis showed that 6 gene (NLRX1, AKT1, CSRP1, LEP, MUC4 and SEMA4B) of 10 genes were abnormal expressions between cancer and paracancer tissue." (PMID 36817485, 2023). "Interestingly, NLRX1 has been shown to regulate autophagy, a cellular process mediated by mitochondrial function, the metabolic state of the cell and ROS production, both in infected and cancer cells and could thus provide a more general mechanism of action." (PMID 33344269, 2020). "In addition, other studies showed that NLRX1 is involved in numerous diseases, including COPD, cancer, deafness, and tumorigenesis." (PMID 36859435, 2023). "In addition, we observed the expression dysregulations of NLRX1, AKT1, CSRP1, LEP, MUC4 and SEMA4B in cancer tissues by immunohistochemistry." (PMID 36817485, 2023). "Moreover, NLRX1 was found to impair mitochondrial ETC activity and inhibit the maturation of precursor transcripts for ETC complexes in cancer cells to attenuate OXPHOS and facilitate aerobic glycolysis." (PMID 33525671, 2021). "The same group showed TUFM-NLRX1 interaction also in cancer cells, in which NLRX1 promoted cetuximab, an epidermal growth factor receptor (EGFR) inhibitor, -induced autophagy and mediated resistance to cancer treatment." (PMID 33344269, 2020). "While more studies are clearly necessary, these findings suggest that NLRX1 may also function, either directly or indirectly, to negatively regulate AKT signaling during cancer." (PMID 27105514, 2016). "However, the expression of NLRX1 in cancerous cells leads to deregulation of EMT and thus facilitates cancer metastasis and increases the disease burden, especially in more aggressive cancers such as TNBC." (PMID 40700427, 2025). "Interestingly multiple studies suggest that NLRX1 promotes oxidative phosphorylation in immune cells but downregulates oxidative phosphorylation and promotes aerobic glycolysis in cancer and non-immune cells, suggesting in this context astrocytes behave more like immune cells." (PMID 39875919, 2025). "NLRX1, a mitochondrial NOD-like receptor (NLR) family protein, is a non-inflammasome-forming protein with diverse roles in cancer." (PMID 42088413, 2026). "NLRX1 inhibited OXPHOS and promoted glycolysis in cancer and non-immune cells; however, NLRX1 increased OXPHOS in immune cells." (PMID 37574163, 2023). "So far, it seems that NLRX1 can promote OXPHOS in immune cells, while supports aerobic glycolysis and attenuates OXPHOS in cancer or non-immune cells." (PMID 33525671, 2021).